MIR507 (microRNA 507)
Synonyms: hsa-mir-507; MIRN507; mir-507
Gene: MicroRNA gene on chromosome X (147,230,984 to 147,231,077, reverse strand). Ensembl gene ENSG00000207969.
Homologues: Orthologues: chimpanzee ptr-mir-507 (100% identical), macaque mml-mir-507 (97% identical), dog MIR507A (77% identical), dog MIR506 (60% identical), macaque mml-mir-506 (56% identical), rabbit ocu-mir-506 (32% identical). Paralogues in human: MIR509-1 (62% identical), MIR513A2 (60% identical), MIR513B (59% identical), MIR514A1 (57% identical), MIR506 (55% identical), MIR514A2 (55% identical), MIR514A3 (55% identical), MIR514B (49% identical), MIR509-3 (46% identical).